FAT1 (FAT atypical cadherin 1)
Diseases named in the same sentence as FAT1 in open-access papers (continued):
Sharing a sentence is not in itself a finding about the gene and the disease.
cancer (continued). "siRNA-mediated FAT1 knockdown in cancer cell lines and in primary cultures led to decreased TGF-β1/2 expression/secretion as assessed by q-PCR, Western blotting, and ELISA." (PMID 35720420, 2022). "FAT1 was also detected in 50% of breast carcinomas studied, with higher mRNA levels corresponding to high-grade cancers." (PMID 35647082, 2022). "Here, we detected 33 FAT1 mutations in ESCC3, including 16 truncating and 6 missense mutations recorded in the Catalog of Somatic Mutations in Cancer." (PMID 35993362, 2022). "The function of FAT1 in both normal and cancer tissues has been studied since FAT1 was discovered in Drosophila." (PMID 35965328, 2022). "By using a pan-cancer cohort with distinct cancer types from MSKCC, we further investigated the ICI predictive roles of FAT1 mutations." (PMID 35739249, 2022). "In The Cancer Genome Atlas (TCGA) HNSCC databases, somatic mutations in FAT1 were associated with lower FAT1 gene expression and increased protein expression of HER3_PY1289." (PMID 35625959, 2022). "For in silico validation, we correlated the expression of TGF-β1 and TGF-β2 genes with FAT1 expression in cases belonging to different cancers using TCGA and GLASS databases." (PMID 35720420, 2022). "In normal keratinocytes and several cancer cell lines, on the other hand, furin-based FAT1 cleavage forms a heterodimer that is subsequently expressed on the cell membrane, where it is susceptible to ectodomain shedding." (PMID 35647082, 2022). "FAT1 and FAT4 have been reported to be frequently mutated in gingivo-buccal OSCCs in an Indian cohort and are associated with tumorigenesis in various cancers including HNSCC." (PMID 34136393, 2021). "FAT1 mutations in GB have already been reported, and studies strongly suggest that members of the FAT gene family are important players in cancer development." (PMID 33922652, 2021). "While FAT1 is still a new candidate in cancer research, GPC3 has been investigated extensively as prognostic biomarker and therapeutic target." (PMID 33878524, 2021). "The revelation of GPC3 as a potential binding partner of FAT1 extracellular domain unfolds an opportunity to study potential triggers of FAT1 signaling in cancers." (PMID 33878524, 2021). "FAT1, the human homolog of Drosophila gene fat, has only been studied over the last decade for its role in embryonic development and cancers." (PMID 33878524, 2021). "A previous study has shown that FAT1 knockdown upregulates MAPK/ERK pathway and promotes epithelial-mesenchymal transition, a hallmark of cancer." (PMID 32974170, 2020). "The results showed that ATM, CHD4, FAT1, KMT2D, MED12, NF2, and SUFU were the most frequently mutated cancer-related genes." (PMID 33193598, 2020). "We found tagSNPs in the FAT1 and COL9A1 gene nearby somatic mutations that drive cancer development were associated with oral malignancy occurrence." (PMID 30657779, 2019).
cancer (continued). "FAT tumor suppressor homolog 4 (FAT4), which belongs to the FAT protein family (FAT1–4) identified in mammals, was first identified as a cancer suppressor in a mouse mammary epithelial cell line." (PMID 30832706, 2019). "Alteration of the cadherin-like protein tumor suppressor FAT1 (FAT atypical cadherin 1) is a recurrent event (>10%) in human cancer." (PMID 31817001, 2019). "More than 25% of HNSCC tumors bear FAT1 mutation or deletion, approximately twice the frequency of EGFR alteration in this cancer type." (PMID 31817001, 2019). "For example, MUC16 was found mutated in 7.4% of cancers (2225 mutated out of 30047 tested samples), MLL2 in 4.8% (1633 out of 34019), FAT1 in 3.81% (1169 out of 30688) and BAI3 in 2.75% (823 out of 30208)." (PMID 30459932, 2018). "To begin addressing FAT1 functions in cancer, we focused on HNSCC, the cancer type in which FAT1 is most frequently mutated and which displays characteristic Hippo signaling dependency, YAP1 overactivity, and frequent YAP1 gene amplification." (PMID 29985391, 2018). "A second set consisted of an additional 15 cancer-related genes (Nf1, Mki67, Mllt4, Fgfr2, Ctnnb1, Fat1, Clp1, Fat4, Arid1a, Nat1, Nat2, Setd2, Impg1, Nbas and Npat)." (PMID 29925311, 2018). "Here, we identify the alteration of FAT1 as a recurrent event in human cancer acting in coordination with other YAP1 activating mechanisms." (PMID 29985391, 2018). "The demonstration of FAT1 expression and D8-FAT1 surface exposition in cancer cell lines prompted us to produce OMVs decorated with mD8-FAT1 with the aim of using mD8-FAT1-decorated OMVs in mouse immunogenicity studies." (PMID 30416985, 2018). "Our data demonstrate that FAT1 functions as an oncogene by influencing cell adhesion, resulting in cancer cell growth promotion although FAT1 function is controversial." (PMID 29228735, 2017). "Gene expression profile reveals that FAT1 expression was up-modulated in cancer tissues compared with normal tissues." (PMID 29228735, 2017). "Mutation frequency in FAT1, NOTCH1 and CASP8 in HNSCC is significantly higher (p < 0.05) in comparison to other cohorts of squamous or similar cancers." (PMID 26506389, 2015). "The increased expression of Fat1 in combination with increased levels of the sheddase ADAM10 in clinically relevant cancer patients suggested that soluble Fat1 should be investigated for its utility as a potential serum biomarker." (PMID 24625754, 2014). "Detection with antibodies directed against the aminoterminus of the Fat1 protein revealed predominantly a single band slightly over 460 kDa in the secretomes with corresponding cell lysates from cancer cells displaying a band of similar mobility." (PMID 24625754, 2014). "Our data derived from the fat-1 transgenic cattle support the notion that a reduced ratio of ω-6/ω-3 fatty acids is favorable for normal cell function and may reduce the risk of certain diseases, such as cardiovascular disease, inflammatory disorders and cancer." (PMID 22206437, 2011). "FAT1 is a transmembrane protein belonging to the cadherin family that has been shown to regulate cell-cell interactions, actin cytoskeleton dynamics and cellular migration in both healthy and cancer cells." (PMID 40458731, 2025). "Moreover, compared with other cancers, FAT1 expression in BRCA showed the strongest positive enrichment with CX3CL1 and numerous CXCL cytokines." (PMID 40083689, 2025). "In addition, the migration and invasion abilities of cancer cells were enhanced after FAT1 knockdown." (PMID 39781458, 2025). "We found NOTCH1 and FAT1 as the most mutated genes, as Martincorena's results in normal skin and esophagus, suggesting the presence of a precancerous or cancer invasion field." (PMID 40465458, 2025).
cancer (continued). "Furthermore, it showed that only patients with FAT1 variants had CRC, and most patients harboured variants in genes such as CHEK2, ERBB2, and KIT in most of the cancers." (PMID 40627234, 2025). "However, the literature regarding FAT4 is generally limited compared to FAT1, particularly cancer related studies." (PMID 40083689, 2025). "Research suggests that FAT1 may play a role in either blocking or promoting carcinogenesis and cancer progression depending on the type of cancer." (PMID 40242237, 2025). "The role of FAT1 in different cancers is considered to be context-dependent and tissue-specific." (PMID 38782965, 2024). "Taken together, these results suggest that FAT1 loss might fuel WGD and elevated CIN, which in turn exacerbates cancer evolution and targeted therapy resistance, as previously demonstrated." (PMID 39738653, 2024). "As one of the most common mutant genes in a variety of cancers, whether FAT1 has a clear mechanism of action in HSCT-related MN requires further investigation." (PMID 38686366, 2024). "Whether these differences in how FAT1 affects cancer cell migration stem from variable effects on EMT or the differential expression of various FAT1 isoforms with distinct subcellular localizations and/or functions is not known." (PMID 37371091, 2023). "The following studies support the Idea that FAT1 promotes cancer cell migration and invasion." (PMID 37371091, 2023). "Considering first therapeutic approaches, a FAT1-derived epitope was successfully tested as anti-CRC cancer vaccine in a murine model and therapeutic antibodies or antibody-conjugated drugs directed against FAT1 for CRC are under development, mechanistically applicable also for T-ALL40–42." (PMID 36653435, 2023). "We found 17 genes with hypomethylation or copy number gain and increased expression, including cancer-associated genes such as AGO1, GHR and FAT1, which might be potential oncogenes." (PMID 37245006, 2023). "Such determinations will require further testing in different cancers, but these same variables could affect how FAT1 affects VSMC migration." (PMID 37371091, 2023). "Knowledge about regulation of aberrant FAT1 expression in cancer is limited." (PMID 36653435, 2023). "While this is true for some cancers, other reports describe FAT1 as pro-migratory." (PMID 37371091, 2023). "Currently, there are limited publications regarding FAT1’s regulation of the cancer immune system." (PMID 35965328, 2022). "In addition to these functions in regulating normal cell activities, FAT1 plays roles in blocking or facilitating carcinogenesis and cancer progression depending on the cancer type." (PMID 35965328, 2022). "Most likely, inactivated FAT1 may regulate cancer progression and metastasis partially through the interaction with Ena/VASP and Homer-mediated cellular cytoskeletal dynamics." (PMID 35965328, 2022). "FAT1 gene, located on chromosome 4q35.2, is the human homolog of Drosophila gene fat and has only been studied in recent years for its role in embryonic development and cancers." (PMID 35720420, 2022). "On the other hand, FAT1 functions as an oncogene in many other cancers." (PMID 35646625, 2022). "Several recent studies have identified circular FAT1 (circFAT1) in cancer cells." (PMID 35965328, 2022). "The alteration frequency of FAT1 is best observed in HNSCC among the various cancers (27.53%)." (PMID 34939311, 2022). "Our study was the first pan-cancer analysis of FAT1 using the TCGA and GEO databases." (PMID 36517565, 2022). "Interestingly, those factors are involved in the acquisition of stemness traits in cancer cells: indeed, Fat1-depleted cells had higher tumorigenic potential, and Fat1-KO mice showed high-spontaneous metastasis rates." (PMID 33498502, 2021). "Overexpression of FAT1 gene and its oncogenic effects have been reported in several cancers." (PMID 31992226, 2020).
cancer (continued). "However, to the best of our knowledge, little was known about FAT1 expression and compartmentalization in mouse cancer cells." (PMID 30416985, 2018). "We posit that these findings may provide an opportunity to investigate the mechanism by which FAT1 regulates YAP in a biologically relevant cancer." (PMID 29985391, 2018). "We also show that unrestrained YAP1 acts as an oncogenic driver in HNSCC, and that targeting YAP1 may represent an attractive precision therapeutic option for cancers harboring genomic alterations in the FAT1 tumor suppressor genes." (PMID 29985391, 2018). "In this work we wanted to investigate whether FAT1-based cancer vaccines could be potentially exploited in CRC immunotherapy." (PMID 30416985, 2018). "Indeed, as judged by quantitative RT PCR analysis of FAT1 mRNA, we found that FAT1 is overexpressed in a number of cancer cell lines, including B16F10 and, particularly, CT26." (PMID 30416985, 2018). "To investigate the function of FAT1 in human cancer, we performed a variety of experiments." (PMID 29228735, 2017). "FAT1, which was highly down-regulated by VP, is involved in cell migration and invasion pathways, and is known to function as an adhesion molecule that contributes to cancer cell survival and migration." (PMID 29228735, 2017). "Other cancer-associated genes in Cluster B include ZEB2, NOTCH1, and FAT1." (PMID 26939613, 2016). "Furthermore, there is evidence for biological interactions between FAT1 and Caspase 8, with FAT1 acting as an antagonist of Caspase 8 in a synthetic lethal screen in cancer cell lines." (PMID 27693639, 2016). "Lastly, though further study is required to show that intake of more than 3 g ω-3 PUFAs/60 kg of body weight can achieve cancer preventive outcomes similar to those seen in fat-1 TG mice, findings from in vitro and in vivo experiments strongly suggest favorable results for ω-3 PUFAs." (PMID 27566583, 2016). "Secondarily, the observation that at 24 weeks, the preservation of 15-PGDH—a PG degrading enzyme—accompanied with attenuated COX-2, VEGF, PDGF, and CD31 expression in Fat-1 TG mice compared to WT mice strongly explained the cancer-preventive actions of ω-3 PUFAs." (PMID 27528223, 2016). "The slightly smaller band present in the cancer cell lysates may represent the N-terminal part of the recently described Fat1 heterodimer, that consists of an N-terminal gp 490 (p420) and a p85 C-terminal transmembrane fragment." (PMID 24625754, 2014). "Hence, we wondered whether FAT1 exerts its cancer-suppressive activity via the modulation of the CSC properties of HNSCC." (PMID 39781458, 2025). "Thus, FAT1 has great potential to serve as a target or prognostic biomarker in cancer treatment." (PMID 35965328, 2022).
cancer (continued). "In view of emerging interest in mitochondrial contributions to macromolecular synthesis and oncometabolite production that support cancer cell growth and phenotype, such mechanisms could be of considerable interest for FAT1-related pathology both within and outside of vascular biology." (PMID 35647082, 2022). "However, in some types of cancer, overexpression of FAT1 leads to EMT." (PMID 35965328, 2022). "In contrast, in some types of cancers, FAT1 may facilitate metastasis." (PMID 35965328, 2022). "However, the present article focuses on the oncogenic aspect of FAT1 in cancer." (PMID 33878524, 2021). "This negative result could be attributed either to a difference in cellular surface expression of FAT1 between human and mouse cancer cells or to the inability of mAb198.3 to bind mD8-FAT1 due to the four amino acid difference present in the D8-FAT1 sequences of the two species." (PMID 30416985, 2018). "It is not clear whether individuals with recessive FAT1 mutations will develop cancer later in life." (PMID 26905694, 2016). "However in an increasing number of reports involving human cancer Fat1 is noted to be altered." (PMID 24625754, 2014). "Indeed, in terms of numbers of peptides identified, which is a relative measure of protein abundance, Fat1 was amongst the most abundant proteins in the cancer cell secretomes representing up to 0.9% of all peptides and the most abundant derivative of any TM protein." (PMID 24625754, 2014). "Subsequently, we examined the correlation between the expression levels of mutant FAT1 in these cases and the IC50 values of drugs accessible in Genomics of Drug Sensitivity in Cancer (GDSC)." (PMID 40407216, 2025). "Specifically, we revealed that FAT1 can phosphorylate CaMKII and further impede the formation of the p-STAT1/IRF9 complex, thereby exerting its role in suppressing cancer." (PMID 39781458, 2025). "FAT atypical cadherin 1 (FAT1), a member of the cadherin superfamily, has attracted research attention in recent years owing to its role in human cancers." (PMID 38782965, 2024). "Taken together, genomic observations and experimental results suggest a role for early positive selection of FAT1 alterations in LUSC tumorigenesis, potentially by driving cancer evolution and WGD through elevated CIN." (PMID 39738653, 2024). "It seems that the effect of FAT1 on drug sensitivity is related to aggressive behaviors, such as stemness and EMT status of cancer cells." (PMID 35965328, 2022). "In invasive ductal breast carcinoma, the cancer cell expression of the protease inhibitor, CSTA and genes involved in adhesion, FAT1, DST, and TMEM45A, were shown to be involved in cancer invasiveness." (PMID 36114508, 2022). "Several other recently identified upstream and downstream regulators of Hippo signaling, including FAT1, SHANK2, Gq/11, and SWI/SNF complex, are more commonly dysregulated in human cancer at the genomic level." (PMID 34150758, 2021). "FAT1, FAT3, and FAT4 are atypical cadherins and key regulators of cancer-relevant cellular processes including planar cell polarity and MST/HIPPO signaling, which regulates organ size." (PMID 33733072, 2021). "It is worth noticing that the number of cancer samples with SHANK2 amplifications way exceeds those with YAP1 amplification, FAT1 deletion, and NF2 deletion, indicating a previously unnoticed role of SHANK2 as a major oncogene." (PMID 34150758, 2021).